YIPF5 (Yip1 domain family member 5)
Description:
Plays a role in transport between endoplasmic reticulum and Golgi. In pancreatic beta cells, required to transport proinsulin from endoplasmic reticulum into the Golgi.
Synonyms: SMAP-5; FINGER5; YIP1A; SB140; YIPFalpha1A; MEDS2; SMAP5
Tractability: Antibody: UniProt predicts a signal peptide or a membrane-spanning region. PROTAC: ubiquitination databases record sites on it; its protein half-life has been measured.
Gene: Protein-coding gene on chromosome 5 (144,158,162 to 144,170,714, reverse strand). Ensembl gene ENSG00000145817.
Subcellular location: Endoplasmic reticulum membrane; Golgi apparatus, cis-Golgi network membrane; Cytoplasmic vesicle, COPII-coated vesicle
Subcellular location (Human Protein Atlas): Endoplasmic reticulum; Golgi apparatus; Vesicles; Nucleoplasm
Gene Ontology:
Molecular function: protein binding
Biological process: insulin processing; regulation of ER to Golgi vesicle-mediated transport; endoplasmic reticulum to Golgi vesicle-mediated transport; vesicle fusion with Golgi apparatus
Cellular component: endoplasmic reticulum; Golgi apparatus; endoplasmic reticulum membrane; COPII-coated ER to Golgi transport vesicle; endomembrane system; endoplasmic reticulum exit site; membrane; nuclear outer membrane-endoplasmic reticulum membrane network
Genetic constraint (gnomAD): Loss-of-function variants: 8 observed, 31.08 expected, observed/expected ratio (o/e) 0.26, 90% interval 0.15 to 0.46. The upper end of that interval is the gene's LOEUF score, 0.46, which puts it in group 2 of 6, group 1 being the genes least tolerant of losing a copy. Missense variants: 282 observed, 317.4 expected, observed/expected ratio (o/e) 0.89, 90% interval 0.81 to 0.98. Synonymous variants: 104 observed, 113.49 expected, observed/expected ratio (o/e) 0.92, 90% interval 0.78 to 1.08.
Homologues: Orthologues: chimpanzee YIPF5 (100% identical), macaque YIPF5 (99% identical), dog YIPF5 (98% identical), pig YIPF5 (97% identical), rabbit YIPF5 (96% identical), guinea pig YIPF5 (95% identical), mouse Yipf5 (93% identical), zebrafish yipf5 (83% identical), tropical clawed frog yipf5 (79% identical), rat Yipf5 (64% identical), Drosophila melanogaster Yip1d1 (47% identical), Caenorhabditis elegans F32D8.14 (46% identical). Paralogues in human: YIPF7 (61% identical), YIPF4 (26% identical), YIPF6 (22% identical).
Diseases named in the same sentence as YIPF5 in open-access papers:
YIPF5 is named in the same sentence as 14 diseases in open-access papers, as found by Europe PMC text mining. Sharing a sentence is not in itself a finding about the gene and the disease. The quoted sentences say what the papers report.
microcephaly (7 papers, 2020 to 2026). A congenital or acquired developmental disorder in which the circumference of the head is smaller than normal for the person's age and sex. "Mutations in YIPF5 cause MEDS2 (microcephaly, epilepsy, and neonatal diabetes syndrome), a fatal disorder manifesting in early childhood." (PMID 41717013, 2026). "For example, impaired ER‐to‐Golgi protein trafficking contributes to ER stress in lipotoxic mouse beta cells, and recessive mutations in YIPF5 disrupt ER‐to‐Golgi trafficking, causing neonatal diabetes and microcephaly through ER stress." (PMID 39119875, 2024). "We report 6 patients from 5 families with a congenital syndrome of neonatal/early-onset diabetes, severe microcephaly, and epilepsy caused by biallelic mutations in the YIPF5 gene." (PMID 33164986, 2020). "In this study, we used genome sequencing to identify recessive pathogenic variants in YIPF5 as the genetic cause of a congenital syndrome characterized by neonatal/early-onset diabetes, severe microcephaly, and epilepsy." (PMID 33164986, 2020). "We report recessive YIPF5 mutations as the genetic cause of a congenital syndrome of microcephaly, epilepsy, and neonatal/early-onset diabetes, highlighting a critical role of YIPF5 in β cells and neurons." (PMID 33164986, 2020). "In conclusion, we report homozygous mutations in YIPF5 as the genetic cause of an autosomal recessive syndrome characterized by microcephaly, epilepsy, and neonatal/early-onset diabetes." (PMID 33164986, 2020). "Yip1 Domain Family Member 5 (YIPF5) is a protein involved in anterograde and retrograde ER to GA transport that is localized at ER exit sites, ER-GA intermediate compartments, and cis-GA with loss-of-function mutations in its encoding gene causing microcephaly accompanied by neonatal diabetes." (PMID 40719631, 2025). "YIPF5 (YIP1 domain family member 5) that leads to ND and microcephaly as well as WFS1 that causes Wolfram Syndrome affect pancreatic β-cell function." (PMID 35640144, 2022). "Our findings suggest that YIPF5 and SURF4 coordinate ER export of key proteins and disruption may underlie cortical development defects leading to microcephaly." (PMID 41717013, 2026). "This was also the case for most described patients with YIPF5-MEDS; however, a recent report described an individual with a homozygous YIPF5 missense variant who, in addition to microcephaly and epilepsy, had illness-induced hyperglycemia, with no insulin requirement between episodes." (PMID 40924476, 2025). "To replicate this finding in a larger unselected cohort, we analyzed the coding regions and exon-intron boundaries of the YIPF5 gene in a further 187 cases diagnosed with diabetes before the age of 12 months (10 also had microcephaly) who did not have a mutation in known monogenic diabetes genes." (PMID 33164986, 2020).
epilepsy (4 papers, 2020 to 2026). A brain disorder characterized by episodes of abnormally increased neuronal discharge resulting in transient episodes of sensory or motor neurological dysfunction, or psychic dysfunction. "Microcephaly, epilepsy, and diabetes syndrome (MEDS) is a congenital disorder with two known etiological genes, IER3IP1 and YIPF5." (PMID 40924476, 2025).
cervical cancer (3 papers, 2017 to 2020). A primary or metastatic malignant neoplasm involving the cervix. "In HeLa and CaSki cells, another human cervical cancer cell line, YIPF5 constitutively activated IRE1 and PERK signaling, with YIPF5-depleted cells showing reduced IRE1 phosphorylation, lower PERK mRNA and protein expression, and less PERK phosphorylation and downstream signaling." (PMID 33164986, 2020).
diabetes (3 papers, 2020 to 2023). "Deletion of YIPF5 caused a 5.5-fold increase in proinsulin staining and a 70% reduction in insulin staining and was associated with a newly described monogenic form of diabetes." (PMID 37537395, 2023).
breast carcinoma (1 paper, 2023). "YIPF5 is a prognostic marker in head, neck, liver, and breast cancers." (PMID 37602329, 2023).
infection (3 papers, 2015 to 2025). The state of being infected such as from the introduction of a foreign agent such as serum, vaccine, antigenic substance or organism. "Western blot analyses confirmed these findings, demonstrating lower levels of PEDV-encoded N protein in YIPF5 KO IPEC-J2 cell lines after infection with PEDV CV777 and LJX." (PMID 40422075, 2025). "Additionally, the overexpression of YIPF5-Flag in IPEC-J2 cell lines followed by infection with PEDV CV777 resulted in increased viral titers and relative mRNA expression of N protein compared to control." (PMID 40422075, 2025). "To further determine when the replication of PEDV begins to be inhibited after the knockout of YIPF5, we monitored PEDV replication every 2 h within 12 h post-infection." (PMID 40422075, 2025). "To further investigate whether YIPF5 plays a role in the infection process of other CoVs, we examined the replication of human coronavirus OC43 (HCoV-OC43) and porcine deltacoronavirus (PDCoV) in WT and YIPF5 KO ACE2-Vero E6 cell lines." (PMID 40422075, 2025). "In HeLa cells, YIPF5 has been shown to interact with and promote IRE1 oligomerization and phosphorylation and enhance downstream XBP1 splicing upon tunicamycin exposure or infection with Brucella abortus." (PMID 33164986, 2020). "The absence of YIPF5 also reduced the infection of HCoV-OC43 and PDCoV." (PMID 40422075, 2025).
tumor (1 paper, 2025). "A deeper analysis revealed upregulation of genes involved in tumor suppression (Clca2, Spink5, Igfbp6, Nptx1, Bex4, Gadd45g, Yipf5), immune regulation (IL6ra, Ccl6, Cd81, Cd244a, Cd151, and Gata4), apoptosis, and pyroptosis (Ddit3, Rgs6, and Gsdmsc2/3/4)." (PMID 39946195, 2025).
YIPF5 also shares sentences with these, for which no sentence is quoted: cancer (1 paper); genetic disease (1); hepatocellular carcinoma (1); Hyperglycemia (1); Primary microcephaly (1); Sepsis (1); Wolfram syndrome (1).